SNORD115-10 (small nucleolar RNA, C/D box 115-10)
Synonyms: HBII-52-10
Gene: Small nucleolar RNA gene on chromosome 15 (25,187,536 to 25,187,616, forward strand). Ensembl gene ENSG00000201943.
Gene Ontology:
Biological process: RNA processing
Cellular component: nucleolus
Homologues: Orthologues: macaque SNORD115 (100% identical), macaque SNORD115 (99% identical), macaque SNORD115 (98% identical), macaque SNORD115 (89% identical). Paralogues in human: SNORD115-12 (100% identical), SNORD115-9 (100% identical), SNORD115-11 (99% identical), SNORD115-13 (99% identical), SNORD115-14 (99% identical), SNORD115-20 (99% identical), SNORD115-21 (99% identical), SNORD115-29 (99% identical), SNORD115-36 (99% identical), SNORD115-40 (99% identical), SNORD115-42 (99% identical), SNORD115-43 (99% identical), and 37 more.